IL1RL1 (interleukin 1 receptor like 1)
Description:
Receptor for interleukin-33 (IL-33) which plays crucial roles in innate and adaptive immunity, contributing to tissue homeostasis and responses to environmental stresses together with coreceptor IL1RAP. Its stimulation recruits MYD88, IRAK1, IRAK4, and TRAF6, followed by phosphorylation of MAPK3/ERK1 and/or MAPK1/ERK2, MAPK14, and MAPK8. Possibly involved in helper T-cell function (Probable). Upon tissue injury, induces UCP2-dependent mitochondrial rewiring that attenuates the generation of reactive oxygen species and preserves the integrity of Krebs cycle required for persistent production of itaconate and subsequent GATA3-dependent differentiation of inflammation-resolving alternatively activated macrophages (By similarity). [Isoform B]: Inhibits IL-33 signaling.
Synonyms: DER4; ST2; T1; FIT-1; ST2L; ST2V; IL33R
Tractability: Antibody: a drug acting on it is in phase 2 or 3 trials; UniProt places it where antibodies can reach, with high confidence; its Gene Ontology location is reachable by antibodies, with high confidence; UniProt predicts a signal peptide or a membrane-spanning region; the Human Protein Atlas places it where antibodies can reach. PROTAC: UniProt records ubiquitination sites on it.
Gene: Protein-coding gene on chromosome 2 (102,311,502 to 102,352,353, forward strand). Ensembl gene ENSG00000115602.
Subcellular location: Cell membrane (Isoform C); Secreted (Isoform B); Cell membrane
Subcellular location (Human Protein Atlas): Plasma membrane; Cytosol; Focal adhesion sites; Predicted to be secreted
Pathways (Reactome):
Signal Transduction: PI5P, PP2A and IER3 Regulate PI3K/AKT Signaling; PIP3 activates AKT signaling
Immune System: Interleukin-33 signaling
Gene Ontology:
Molecular function: interleukin-33 receptor activity; protein binding; cytokine receptor activity; interleukin-33 binding; interleukin-1 receptor activity; NAD+ nucleosidase activity, cyclic ADP-ribose generating
Biological process: interleukin-33-mediated signaling pathway; immune response; inflammatory response; macrophage differentiation; signal transduction; negative regulation of T-helper 1 type immune response; negative regulation of type II interferon production; positive regulation of chemokine production; positive regulation of inflammatory response; positive regulation of interleukin-5 production; positive regulation of macrophage activation
Cellular component: plasma membrane; cell surface; receptor complex; external side of plasma membrane; extracellular region
Genetic constraint (gnomAD): Loss-of-function variants: 20 observed, 27.35 expected, observed/expected ratio (o/e) 0.73, 90% interval 0.51 to 1.06. The upper end of that interval is the gene's LOEUF score, 1.06, which puts it in group 4 of 6, group 1 being the genes least tolerant of losing a copy. Missense variants: 544 observed, 489.38 expected, observed/expected ratio (o/e) 1.11, 90% interval 1.03 to 1.19. Synonymous variants: 196 observed, 180.85 expected, observed/expected ratio (o/e) 1.08, 90% interval 0.96 to 1.22.
Homologues: Orthologues: macaque IL1RL1 (93% identical), pig IL1RL1 (68% identical), mouse Il1rl1 (67% identical), rabbit IL1RL1 (65% identical), rat Il1rl1 (64% identical), guinea pig IL1RL1 (62% identical). Paralogues in human: IL1R1 (28% identical), IL1RAPL2 (26% identical), IL1RL2 (26% identical), IL1RAPL1 (24% identical), IL18R1 (24% identical), IL18RAP (23% identical), IL1RAP (23% identical), LAG3 (14% identical), IL1R2 (12% identical), SIGIRR (12% identical).
Diseases named in the same sentence as IL1RL1 in open-access papers:
IL1RL1 is named in the same sentence as 146 diseases in open-access papers, as found by Europe PMC text mining. Sharing a sentence is not in itself a finding about the gene and the disease. The quoted sentences say what the papers report.
asthma (126 papers, 2009 to 2025). "Consistent with the association between high DNAm scores and T2-high asthma, we observed overexpression of canonical T2 genes implicated in the pathways or directly targeted by current biologic therapeutics, including IL1RL1, CCR3, and IL5RA10,53,54." (PMID 40950420, 2025). "According to genome-wide association studies, the genes encoding these genes (IL33 and IL1RL1) are associated with asthma susceptibility." (PMID 41087719, 2025). "For example, a cis-pQTL for interleukin 1 receptor like 1 (IL1RL1), a cytokine that helps mediate allergic immune responses, was associated with eosinophil counts and asthma." (PMID 39316441, 2024). "The interleukin‐33/interleukin‐1 receptor‐like‐1 (IL‐33/IL1RL1) signalling pathway is implicated in asthma pathogenesis, with IL1RL1 nonsynonymous genetic polymorphisms associated with disease risk." (PMID 39301832, 2024). "Significantly, our data identified that maximal IL1RL1 signalling occurs in cells carrying both asthma IL1RL1 risk variants in the extracellular and TIR domains, that is, the protein sequence that contains Ala78 and Ala433‐Glu501‐Thr549‐Leu551 together." (PMID 39301832, 2024). "Together with the IL33 locus, one of the most highly reproduced association signals in genome‐wide association studies of asthma, spans the IL1RL1 gene." (PMID 39301832, 2024). "When measuring IL8 levels we observe a similar response but with a different dose–response relationship compared with the promoter–reporter (SEAP) data, that is, the presence of both the asthma risk alleles was required for maximal IL1RL1 signalling." (PMID 39301832, 2024). "The elevated genes include those associated with cellular proliferation (BRICD5), those previously associated with asthma and other inflammatory diseases (IL1RL1, IL6R) and those involved in inflammatory cell signaling (LIME1) and function (SLC11A1)." (PMID 37876037, 2023). "A genome-wide association study indicated that rs13431828 and rs1041973 in IL1RL1 were associated with childhood asthma susceptibility in the Mexican population." (PMID 37719702, 2023). "A previous study indicated that IL1RL1 rs1420101 was associated with high exhaled nitric oxide and blood eosinophil differentials among Japanese patients with asthma." (PMID 37719702, 2023). "A recent study demonstrated that genetic variations in IL1RL1 are strongly associated with asthma, revealing that IL1RL1 acts as an essential driver of type 2 immune responses to IL-33." (PMID 37206297, 2023). "IL-33, a member of the IL-1 cytokine family, is constitutively expressed by both epithelial and endothelial cells, and genetic variations of IL33 and its receptor IL-1RL1 (ST2) have been associated with asthma in humans." (PMID 37759430, 2023). "In their work, the A-allele of rs1420101 located in IL1RL1 was associated with a lower probability of complete asthma remission in adults." (PMID 37761964, 2023). "In a genome-wide association study, genetic variants of IL33 and IL1RL1 were significantly associated with asthma." (PMID 36674744, 2023). "Another gene-related research presented that IL-33 is related to asthma and that both IL-33 and IL1RL1 are linked to disease susceptibility." (PMID 37153553, 2023). "A meta‐analysis in 2,007 children in Prevention and Incidence of Asthma and Mite Allergy (PIAMA) and 7,247 in ALSPAC found that SNPs encoding IL33 and IL1RL1 were associated with asthma, intermediate and late‐onset wheeze phenotypes." (PMID 35338742, 2022). "The childhood asthma susceptibility gene IL-1RL1, which encodes the receptor of the epithelial alarmin IL-33, is known to promote airway inflammation." (PMID 35197433, 2022). "Expression of Il33 or Il1rl1 genes also correlates with susceptibility to asthma, as well as the type 2 response in murine experimental asthma models, further supporting a crucial role of IL-33-mediated ILC2s activation during allergy." (PMID 34194431, 2021).
asthma (continued). "In conclusion, we found significant associations between IL1RL1 rs10208293 and rs13424006 polymorphisms and the risk of childhood asthma." (PMID 34977013, 2021). "The A allele of rs10208293 and C allele of rs13424006 in IL1RL1 both were associated with lower susceptibility to asthma and lower FeNO." (PMID 34977013, 2021). "GWAS have reproducibly found that genetic variations in IL-33 and IL1RL1 genes alter IL-33/IL-1RL1 pathway through different molecular changes in gene transcription or protein synthesis, and correlate with increased asthma susceptibility." (PMID 33925009, 2021). "Another large-scale GWAS for asthma has identified six asthma-susceptible loci, including IL1RL1/IL18R1, SMAD3, ORMDL3/GSDM, IL-33, IL2RB, and HLA-DQ." (PMID 34946955, 2021). "IL18R1 and IL1RL1 have been shown in many studies to have variants associated with asthma as well as having altered expression profiles in asthmatic subjects." (PMID 35386986, 2021). "In CD4+ T cells, the IL-33/ST2 signaling pathway plays an important role in Th2 activation, and interestingly, IL1RL1 variants are linked to increased risk of IL-33-driven type 2 inflammation in asthma." (PMID 33924911, 2021). "In this multiple-cohort study, we extend a priori evidence that genetic variation in the IL1RL1 region is important for asthma susceptibility and blood eosinophil counts." (PMID 32324168, 2020). "We provide insight into the nature of the genetic association with clinical and immunological features of asthma and the mechanistic underpinnings of these associations with respect to IL1RL1 expression and activity." (PMID 32324168, 2020). "We identified that all of our signals of interest were able to modulate response to HDM, a common allergen associated with asthma and allergies, on IL1RL1 expression in HBECs." (PMID 32324168, 2020). "In agreement with other reports, we show that the asthma risk haplotype leads to enhanced NF-κB activity after IL-33–mediated IL1RL1 signaling in a reductionist cell model." (PMID 32324168, 2020). "Given the association between eosinophils and asthma, it is worth noting that IL1RL1, IL1RL2, IL2RA, and IL4R are all linked to ‘Eosinophil count’ and ‘Eosinophil percentage’ in GeneAtlas." (PMID 32628676, 2020). "In summary, these data show that 3 of our prioritized signals are eQTLs for IL1RL1 in lung tissue; however, the 2 asthma-associated risk alleles have opposite directions of effect on IL1RL1 mRNA expression in lung tissue." (PMID 32324168, 2020). "Association between IL1RL1 SNPs and baseline IL1RL1 expression in cultured bronchial epithelial cells from asthma patients." (PMID 32324168, 2020). "Significant associations between genetic variants of IL33 and IL1RL1 and human asthma have consistently been identified in several genetic studies, suggesting that the IL-33/ST2-axis is likely to play a role in the disease." (PMID 33255348, 2020). "One of the most replicated asthma-associated genetic signals is the chromosome 2q12 locus, containing the IL-1 receptor like 1 (IL1RL1), IL18R1, and IL-18 receptor accessory protein (IL18RAP) genes." (PMID 32324168, 2020). "The presence of multiple polymorphisms in the IL1RL1 locus that independently contribute to asthma risk complicates the interpretation of the association signal with the disease." (PMID 32324168, 2020). "We tested for association between IL1RL1 region SNPs and characteristics of asthma as defined by clinical and immunological measures and addressed functional effects of these genetic variants in lung tissue and airway epithelium." (PMID 32324168, 2020). "In Signal A (tagged by rs995514), there was a modest increase in the level of soluble IL1RL1 protein (1.63-fold) in the presence of the asthma protective allele (C)." (PMID 32324168, 2020). "Using GeneAtlas data, our analysis finds 5 proteins—all interleukin receptors—whose levels causally contribute to asthma disease risk: IL1RL1, IL1RL2, IL2RA, IL4R, and IL6R." (PMID 32628676, 2020).
asthma (continued). "Overall, these data suggest that asthma and asthma phenotype–related risk alleles, as part of distinct genetic signals at the IL1RL1 locus, significantly affect IL1RL1 mRNA and protein levels in a tissue- and isoform-specific way." (PMID 32324168, 2020). "The other main splice variant encodes the soluble form of the receptor (sST2, IL1RL1-a), which has been detected in both bronchoalveolar lavage fluid and serum in asthma patients." (PMID 32324168, 2020). "In Signal C (tagged by rs17027258), presence of the severe asthma risk allele (A) identified modest elevation in IL1RL1 soluble protein expression after HDM stimulation (1.5-fold; P < 0.01)." (PMID 32324168, 2020). "This study has significantly advanced our understanding of both the phenotypic and the functional effects of polymorphisms in the IL1RL1 locus in the context of asthma." (PMID 32324168, 2020). "We set out to extend our understanding of the IL1RL1 locus in asthma, one of the most reproducible association signals identified to date, with a particular focus to the contribution of the IL1RL1 gene." (PMID 32324168, 2020). "The asthma risk allele for Signal C (proxy rs11690532 [C]), however, was associated with elevated IL1RL1 mRNA expression (of both transcripts in a combined and independent assay)." (PMID 32324168, 2020). "In several genome wide association (GWA) studies it has been established that both genes encoding IL-33 and its receptor IL1RL1 are susceptibility loci for asthma." (PMID 31057533, 2019). "The results of studies carried out in the Brazilian population demonstrate a strong relationship between the genetic variants of the gene encoding IL-33 and IL1RL1 with allergy and asthma markers." (PMID 30304837, 2018). "The meta-analysis of NHW and AA subjects in out childhood asthma GWAS found association with IL1RL1 (rs4988958, adjusted p = 0.035) and LINC01149 (rs2596464, adjusted p = 0.017)." (PMID 30373671, 2018). "Associations were found in the current childhood asthma GWAS with known asthma loci in IL1RL1, IL13, LINC01149, near GSDMB, and in the C11orf30-LRRC32 region (Bonferroni adjusted p < 0.05 for all comparisons)." (PMID 30373671, 2018). "Genome wide association studies have identified single nucleotide polymorphisms (SNPs) in the IL1RL1 gene that are associated with asthma." (PMID 30174671, 2018). "Genome-wide association studies (GWASs) have demonstrated that IL-33 and IL1RL1 (encoding the IL-33 receptor) variants were associated with arising asthma and blood eosinophilia." (PMID 30176857, 2018). "Among the NHW population, the childhood asthma GWAS found association with TAGC pediatric asthma SNPs in IL1RL1 (rs4988958, adjusted p = 0.002), LINC01149 (rs2596464, adjusted p = 0.021), and near the GSDMB region (rs8069176, adjusted p = 0.041)." (PMID 30373671, 2018). "We showed associations with known asthma loci in IL1RL1, IL13, LINC01149, near GSDMB, and in the C11orf30-LRRC32 region." (PMID 30373671, 2018). "Different studies have indicated that IL1RL1 is increased in severe asthma and is associated with multiple indicators of TH2-like inflammation, including blood eosinophils, exhaled nitric oxide, epithelial CLCA1 and eotaxin-3." (PMID 30598657, 2018). "The genes encoding IL-33 and ST2/IL1RL1 have been identified as major susceptibility loci for human asthma in several genome-wide association studies." (PMID 29977243, 2018). "Accordingly, common variants in IL1RL1 that associate with increased asthma risk associate with reduced expression of soluble ST2, with the predicted effect being increased IL-33 activity, due to reduced level of this decoy receptor." (PMID 28273074, 2017). "Association of common sequence variants in IL33 and IL1RL1 with eosinophil counts and asthma in Iceland." (PMID 28273074, 2017). "Our results indicate that variants at the IL1RL1 locus affect eosinophil counts and the risk of asthma most likely by affecting IL1RL1 itself." (PMID 28273074, 2017).
asthma (continued). "Clinically, IL1RL1 genetic polymorphisms and IL1RL1-a serum levels have been associated with severe arthritis, acute heart disease, and airway disease such as asthma." (PMID 22574108, 2012). "Collectively, there is strong evidence for genetic association of IL1RL1 with asthma and related phenotypes." (PMID 21629437, 2010). "Two-gene models implicating functional variants in the IL10 and VDR genes as well as in the IL10 and IL1RL1 genes were associated with asthma (p < 0.0002)." (PMID 19852851, 2009). "Our preliminary results confirm that three asthma susceptibility loci: 2q12.1 (IL1RL1), 6p21.32 (HLA-DQA1/B1/A2/B2), and 22q12.3 (IL2RB) each have VDR- and IKZF3-binding sites either in enhancers predicted by GeneHancer to target these genes or within these genes themselves." (PMID 38567749, 2024). "Previous reports have suggested that the IL-33-ST2 (IL-1RL1) axis is the root cause of asthma." (PMID 38397588, 2024). "In addition, rs1420101 was strongly associated with IL1RL1 methylation and serum IL1RL1-a levels in asthma." (PMID 37719702, 2023). "In addition, IL‐33 and IL1RL1 (ST2) variants are reported to be significantly associated with asthma." (PMID 37357549, 2023). "Associations between IL‐33 and IL1RL1 genetic variants have been reported for asthma." (PMID 35986608, 2023). "Furthermore, polymorphisms in IL33 and IL1RL1 have been associated with an increased risk of asthma in several genome-wide association studies involving a diverse range of geographical populations." (PMID 37607012, 2023). "Recent evidence suggests that single nucleotide polymorphisms (SNPs), such as in the interleukin 1 receptor-like 1 (IL1RL1) or on the chromosome 17q21, may play an import role in the risk and time-to-onset of asthma." (PMID 35453508, 2022). "Indeed, IL33 and its Interleukin 1 receptor-like 1 (IL1RL1) receptor are among the most highly replicated susceptibility loci for asthma." (PMID 34930320, 2021). "GWASs have reproducibly found the IL1RL1 gene to be associated with asthma susceptibility." (PMID 33133517, 2020). "However, some caveats in the data are observed — in particular, that asthma risk alleles at different signals have opposing effects on IL1RL1 expression, although this is supported by other studies and potentially highlights the complexity of this locus." (PMID 32324168, 2020). "In this study, we set out to extend the association of the IL1RL1 region polymorphisms with asthma diagnosis and to define the relative contribution of SNPs spanning the association signal to characteristics of asthma defined by clinical and immunological measures." (PMID 32324168, 2020). "IL1RL1 coding region variants associated with asthma influence signaling." (PMID 32324168, 2020). "Interestingly, we found the DER at IL1RL1 (also known as the IL33 receptor ST2) overlapped previously identified asthma-associated SNPs." (PMID 33362848, 2020). "This was also observed for asthma-associated IL1RL1 nonsynonymous coding TIR domain SNPs." (PMID 32324168, 2020). "Notably, IL-33 and ST2/IL1RL1 (IL-33 receptor) genes are considered to be asthma disease susceptibility genes and have been identified in genome-wide association studies." (PMID 31616416, 2019). "The meta-analysis of NHW and AA subjects in our childhood asthma GWAS found association with known asthma variants in IL1RL1 (rs10197862, adjusted p = 0.042), in IL13 (rs1295686, adjusted p = 0.043), and near the C11orf30-LRRC32 region (rs7130588, adjusted p = 0.005)." (PMID 30373671, 2018). "Among the NHW population, the childhood asthma GWAS found association with a known asthma variants in IL1RL1 (rs10197862, adjusted p = 0.011) and approached significance in GSDMB (rs2305480, adjusted p = 0.060) and near the C11orf30-LRRC32 region (rs7130588, adjusted p = 0.054)." (PMID 30373671, 2018).